FKBPL (FKBP prolyl isomerase like)
Diseases named in the same sentence as FKBPL in open-access papers (continued):
Sharing a sentence is not in itself a finding about the gene and the disease.
chronic lymphocytic leukemia (1 paper, 2024). "This integrative analysis identified genes whose dysregulation may explain the links between JIA and associated traits, such as autoimmune/inflammatory diseases (genes at 6p22.1 locus), Hodgkin lymphoma (genes at 6p21.3 [FKBPL, PBX2, AGER]), and chronic lymphocytic leukemia (BAK1)." (PMID 39175752, 2024). "Notably, in addition to HLA class II genes (which might contribute to chronic inflammation), we found a distinct association between JIA and Hodgkin lymphoma through a set of genes in 6p21.3 (FKBPL, PBX2, AGER); and chronic lymphocytic leukaemia through the BAK1 gene." (PMID 39175752, 2024).
depression (1 paper, 2023). "While NOx is extensively studied in stress and depression, this is, to our knowledge, the first report to show a role for FKBPL in such disorders, suggesting that FKBPL upregulation is associated with stress and depression disorders." (PMID 37375593, 2023). "The aim of this study was to investigate the potential antidepressant and anxiolytic effects of vitamin C and vitamin D in a stress-induced mouse model of depression, while also exploring the association between these effects and the levels of circulating NOx, periostin, and FKBPL." (PMID 37375593, 2023). "In conclusion, the study establishes the potential antidepressant effects of vitamin C and vitamin D mediated by NOx and FKBPL levels, as well as the crucial role of periostin in depression." (PMID 37375593, 2023). "Future studies should examine NOx, periostin, and FKBPL in the hippocampus and prefrontal cortex, two critical brain regions involved in depression, to provide a full picture of how these biomarkers are related to depressive symptoms." (PMID 37375593, 2023). "Alternatively, vitamin C, vitamin D, and escitalopram were able to normalize the elevated FKBPL and NOx levels seen in stress-induced depression." (PMID 37375593, 2023). "On the other hand, the increased levels of FKBPL and NOx in stress-induced depression were normalized by the administration of vitamin C, vitamin D, and escitalopram." (PMID 37375593, 2023). "Vitamin C, vitamin D, and escitalopram were able to correct stress-induced depression’s elevated levels of FKBPL and NOx." (PMID 37375593, 2023). "Furthermore, FKBPL and NOx levels were increased in stress-induced depression and normalized by treatment with vitamin C, vitamin D, and escitalopram, indicating their involvement in the stress response and gene expression regulation." (PMID 37375593, 2023). "Overall, our findings suggest that vitamin C, vitamin D, and escitalopram may possess antidepressant properties mediated by NOx and FKBPL levels, while emphasizing the potential significance of periostin in the context of depression." (PMID 37375593, 2023).
endometrioid endometrial carcinoma (1 paper, 2022). "The role of FKBPL in angiogenesis, growth, and carcinogenesis of endometrioid endometrial carcinoma (EEC) is still largely unknown." (PMID 36295491, 2022).
hyperglycaemia (1 paper, 2021). "Furthermore, we demonstrated in relevant in vitro models that FKBPL and SIRT-1 proteins are reduced in both the presence of hyperglycaemia and lower oxygen tension (relevant for placental development) that could have adverse effects on trophoblast function and placental development." (PMID 34149611, 2021).
hypertrophic cardiomyopathy (1 paper, 2023). A condition in which the myocardium is hypertrophied without an obvious cause. "In human plasma samples, FKBPL concentration was increased in HFpEF compared to controls (p < 0.01); however, similar to NT-proBNP and Gal-3, it was unable to stratify between different forms of HFpEF: acute HFpEF, chronic HFpEF and hypertrophic cardiomyopathy (HCM)." (PMID 36830764, 2023).
hypertrophy (1 paper, 2023). Hypertrophy is the increase in the volume of an organ or tissue due to the enlargement of its component cells. "Finally, FKBPL was positively correlated with an echocardiography parameter reflective of cardiac microvascular dysfunction and hypertrophy, further strengthening the evidence for its role in the pathogenesis of HFpEF." (PMID 36830764, 2023).
lung adenocarcinoma (1 paper, 2024). A carcinoma that arises from the lung and is characterized by the presence of malignant glandular epithelial cells. "However, the role of FKBPL in lung adenocarcinoma (ADC) remains unclear." (PMID 38164287, 2024).
lung carcinoma (1 paper, 2025). "For example, FKBPL was associated with parental history of lung cancer, hip circumference, and vigorous physical activity levels, while PDIA3 was linked to parental history of lung cancer and body mass index." (PMID 41463415, 2025).
serous ovarian cancer (1 paper, 2024). "Moreover, high endogenous tumour expression of FKBPL was significantly associated with increased progression-free survival in patients with high-grade serous ovarian cancer." (PMID 38164287, 2024). "A recent study on high-grade serous ovarian cancer shows that patients with high endogenous tumour expression of FKBPL have an increased progression-free survival." (PMID 38164287, 2024).
triple-negative breast carcinoma (1 paper, 2019). An invasive breast carcinoma which is negative for expression of estrogen receptor (ER), progesterone receptor (PR), and human epidermal growth factor receptor 2 (HER2). "Here, we show for the first time, that FKBPL and its therapeutic peptides reduce metastatic burden in a triple negative breast cancer model and inhibit endocrine therapy resistant CSCs, thereby reducing tumour initiation, in ER+ disease." (PMID 30975104, 2019). "In triple negative breast cancer using MDA-MB-231 cells, we demonstrated FKBPL-mediated differentiation of CSCs to more “mature” cancer cells, no cytotoxic effect and inhibition of cell migration, invasion and metastasis." (PMID 30975104, 2019). "Similar to the triple negative breast cancer cell line, MDA-MB-231, FKBPL overexpression in MCF-7 cells resulted in a reduction in the number of holoclones and concomitant increase in the number of differentiated colonies while the overall colony number remained the same (p < 0.001)." (PMID 30975104, 2019).
cancer (18 papers, 2013 to 2025). A tumor composed of atypical neoplastic, often pleomorphic cells that invade other tissues. "FKBPL/WISP39 has been associated with cancer, regulation of tumour growth and angiogenesis, its high expression being positively evaluated for improved patient survival, most likely due to stabilization of newly synthesised cyclin-dependent kinase inhibitor, p21." (PMID 30717249, 2019). "Furthermore, loss of the region of chromosome 6, on which FKBPL is located, has been shown to occur more frequently in patients presenting with cancer recurrence within 5 years of diagnosis." (PMID 25906750, 2015). "Several studies have demonstrated the important anti-cancer role of FKBPL and its therapeutic peptide derivatives, AD-01 (a preclinical peptide candidate) and ALM201 (clinical peptide candidate), which target angiogenesis via CD4414,15." (PMID 40069829, 2025). "FKBPL, a novel member of the immunophilin family, has emerged as a potential cancer biomarker and therapeutic target." (PMID 41048997, 2025). "FKBPL-based therapeutic peptide mimetic, AD-01 (preclinical peptide candidate), has showed a potent anti-angiogenic and anti-cancer stem cell effects in cancer via CD44 and DLL4." (PMID 40109359, 2025). "We have previously shown that overexpression of FKBPL inhibited migration and invasion of cancer cells." (PMID 34149611, 2021). "Reduced FKBPL levels, leading to enhanced angiogenesis, implicates a possible role in diseases other than cancer, such as cardiovascular and wound healing disease, thus extending the therapeutic utility of targeting FKBPL." (PMID 25767277, 2015). "Nevertheless, previous studies have tested AD-01 as a preclinical FKBPL-based peptide candidate therapeutic in various in vivo models of cancer whereas ALM201 (a clinical FKBPL-based peptide candidate therapeutic) was also tested in Phase I clinical trials, showing favourable safety profile." (PMID 40069829, 2025). "Furthermore, we have demonstrated that the ability of FKBPL to bind CD44 makes it useful for targeting cancer stem cells (CSCs), which express high levels of CD44." (PMID 25906750, 2015). "Recently another member of the FKBP family has emerged FKBP-like or FKBPL that may have high significance in cancer." (PMID 24278769, 2013). "Given limited success from VEGF-targeting approaches and positive correlations between CD44 expression and enhanced angiogenic properties of cancer cells, the FKBPL peptide may prove advantageous in the field of novel anti-angiogenic agents currently in clinical use." (PMID 23457460, 2013). "FK506-binding protein-like (FKBPL)-based therapeutics, AD-01 and ALM201, showed toxicity against cancer stem cells (CSCs), which are resistant to endocrine therapy." (PMID 35631583, 2022). "As a FK506 binding protein like (FKBPL) peptide derivative, ALM-201 can bind to CD44 and inhibit cancer related pathways, such as DLL4/NOTCH signal pathway as well as inhibit cell migration, tubule formation and angiogenesis." (PMID 31552191, 2019). "A ‘first-in-class’ FKBPL-based anti-angiogenic therapeutic peptide, ALM201, will shortly enter a multi-centre cancer clinical trial (EudraCT 2014–001175-31)." (PMID 25906750, 2015). "However, metformin, aspirin and resveratrol have been extensively tested in vivo and in human studies including pregnancy, whereas FKBPL-based therapeutic peptides (AD-01 and ALM201) have only been tested in the context of cancer." (PMID 40109359, 2025). "Except FKBPL and FKBP12, peptidyl-prolyl isomerases are ones of the endogenous drivers of cancer stemness, which control different points in tumor cell regulation, including gene transcription, signaling networks, the mitochondrial permeability transition pore, and others." (PMID 32268506, 2020). "However, a sizable number of the co-chaperones, including HspBP1, the JDP family proteins, FKBPL, and TTC4 appear to signal a good prognosis in cancer suggesting that they may have tumor suppressive functions." (PMID 24278769, 2013).
tumour (13 papers, 2013 to 2025). "High endogenous tumour expression of FKBPL was associated with an increased progression-free interval, supporting the protective role of FKBPL in HGSOC." (PMID 31772325, 2020). "Others such as the J domain protein family, HspBP1, TTC4, and FKBPL appear to be associated with more benign tumor phenotypes." (PMID 24278769, 2013). "FKBPL expression was associated with tumour differentiation (P = 0.037)." (PMID 38164287, 2024). "Dysregulated expression of FK506-binding protein like (FKBPL) has been demonstrated to play crucial roles in tumour development." (PMID 38164287, 2024). "Patients with well or moderately differentiated tumours have higher FKBPL expression compared with patients with poor differentiated tumours." (PMID 38164287, 2024). "Patients with well or moderately differentiated tumours have higher FKBPL expression compared with patients with poor differentiated tumours (P = 0.037)." (PMID 38164287, 2024). "Immunohistochemical staining of the whole tissue sections showed that FKBPL was predominantly localized in the cytoplasm, and its expression levels were decreased in tumours compared with the matching normal tissues." (PMID 38164287, 2024). "Patients with well or moderately differentiated tumours had higher FKBPL expression compared with patients with poor differentiated tumours." (PMID 38164287, 2024). "The plasmid DNA treatment resulted in upregulated production of FKBPL in the tumor, reduced vasculature, reduced tumor sizes, and prolonged survival times." (PMID 37298407, 2023). "Part of this study examined tumor growth in a FKBPL knockdown mouse model, confirming increased vascular sprouting and tumor growth." (PMID 36295491, 2022). "The same study showed that the administration of purified recombinant FKBPL and its peptide derivative, AD-01, inhibited the migration of tumor cells." (PMID 36295491, 2022). "The study concluded that FKBPL is an endogenous secreted antiangiogenic protein, whose downregulation in neoplastic cells allows uncontrolled tumor growth potential." (PMID 36295491, 2022). "FK506-binding protein like (FKBPL) is a novel anti-tumour protein that belongs to the family of immunophilins, but is a divergent member lacking peptidyl prolyl isomerase activity." (PMID 30975104, 2019). "Secreted FK506-binding protein like (FKBPL) and its peptide derivatives inhibit cell migration and tumor angiogenesis by targeting CD44." (PMID 25767277, 2015). "FK506-binding protein-like (FKBPL) has established roles as an anti-tumor protein, with a therapeutic peptide based on this protein, ALM201, shortly entering phase I/II clinical trials." (PMID 25906750, 2015). "For scoring FKBPL, sections/cores were assigned overall FKBPL staining intensity scores; 0, 1+, 2+ or 3+ providing over 20% of the core consisted of tumor tissue." (PMID 25906750, 2015). "This confirms our earlier studies on the CD44-dependent effect of FKBPL on migration of tumor and endothelial cells, further strengthening the role of zCd44 as zFkbpl’s extracellular membrane target." (PMID 25767277, 2015). "Although the role of FKBPL on tumor angiogenesis has been extensively investigated; its endogenous role in physiological or developmental angiogenesis has not yet been elucidated." (PMID 25767277, 2015). "Nevertheless, the data generated through this collectively large patient cohort support the emerging in vitro and in vivo data highlighting FKBPL's anti-tumor activity." (PMID 25906750, 2015). "FK506 binding protein-like (FKBPL) and its peptide derivatives exert potent anti-angiogenic activity in vitro and in vivo and control tumour growth in xenograft models, when administered exogenously." (PMID 23457460, 2013). "In vivo, FKBPL overexpressing tumour xenografts develop a compromised tumour vasculature consistent with FKBPL’s role as a secreted anti-angiogenic protein." (PMID 23457460, 2013).
tumour (continued). "The anti-migratory effect of rFKBPL also showed a dependency on CD44 expression in PC3 cells transfected with CD44 targeted siRNA, indicating that FKBPL/AD-01 can mediate anti-migratory effects in tumour cells by targeting CD44." (PMID 23457460, 2013). "Intravital microscopy demonstrated impaired vascular development in FKBPL overexpressing tumours compared to MDA-MB-231 controls." (PMID 23457460, 2013). "Substantial evidence indicates that FKBPL functions as a tumour suppressor." (PMID 38164287, 2024). "FKBPL has been shown to function as a tumour suppressor in various types of human malignancies." (PMID 38164287, 2024). "FKBPL is a member of the immunophilin protein family that may inhibit angiogenesis and tumor growth by CD44 receptor dependent mechanisms." (PMID 37298407, 2023). "Based on our previously published work we have established that the FKBPL pre-clinical peptide, AD-01, could inhibit both endothelial and tumour cell migration in a CD44-dependent manner." (PMID 30975104, 2019). "FKBPL has diverse anti-tumour roles both as an intracellular and extracellular protein." (PMID 30975104, 2019). "Therefore, since FKBPL demonstrates clear inhibitory roles in tumor growth and progression through a variety of independent mechanisms, its potential as a prognostic biomarker was further explored here in 5 independent TMA cohorts using IHC." (PMID 25906750, 2015). "In murine angiogenesis models, including the ex vivo aortic ring assay, in vivo sponge assay, and tumor growth assay, Fkbpl+/− mice exhibited increased sprouting, enhanced vessel recruitment, and faster tumor growth, respectively, supporting the antiangiogenic function of FKBPL." (PMID 25767277, 2015). "Although secretion of FKBPL has not been observed by the parental MDA-MB-231 cells, FKBPL overexpressing MDA-MB-231 cells demonstrated FKBPL secretion invitro; this secretion, if occurring invivo would support the FKBPL-mediated anti-angiogenic effects on the murine tumour endothelium." (PMID 23457460, 2013). "Histoscores were used so that statistical evaluation of FKBPL levels across all cohorts could be standardised and where percentage tumour stained could also be considered; thus allowing FKBPL to be categorised into low and high levels according to the median value of 190, across all cohorts." (PMID 25906750, 2015). "Furthermore, MDA-MB-231 tumour cells stably overexpressing FKBPL inhibited tumour vascular development in vivo suggesting that FKBPL secreted from tumour cells could inhibit angiogenesis." (PMID 23457460, 2013). "Another in vivo study compared the local tumor injection of siRNA and plasmid DNA targeting the FK506-binding protein such as the –FKBPL gene (pFKBPL)." (PMID 37298407, 2023). "FKBPL-based therapy can (i) dually target angiogenesis and CSCs, (ii) target the CD44/STAT3 pathway in tumours and (iii) is effective in highly vascularised HGSOC tumours with low levels of IL-6." (PMID 31772325, 2020). "HGSOC therefore remains a disease of unmet clinical need, and here, for the first time, we evaluate a FKBPL peptide fragment, ALM201, to dual-target HGSOC stem cells and tumour angiogenesis." (PMID 31772325, 2020). "Our data demonstrates after adjusting for tumor size, grade, nodal status, ER and PR status and also HER2 status, FKBPL remains significant." (PMID 25906750, 2015). "We have demonstrated that FKBPL and AD-01 bind to the CD44 receptor and inhibit tumour cell migration in a CD44 dependant manner; CD44 knockdown abrogated AD-01 binding as well as its anti-migratory activity." (PMID 23457460, 2013). "The anti-FKBPL siRNA (2 mg, 2×/wk) did not affect tumor size but did appear to increase tumor angiogenesis." (PMID 37298407, 2023). "In EEC tumor cells, data showed expression varying from none to low and rarely of moderate intensity, whereas the information on FKBPL expression within stromal cells of EEC was not reported." (PMID 36295491, 2022).
tumour (continued). "Furthermore, we elucidate additional targets of FKBPL such as DLL4 and Notch 4, which in addition to CD44, are potentially involved in the multiple anti-tumour effects of FKBPL and its therapeutic peptide derivatives." (PMID 30975104, 2019). "Thus the anti-angiogenic protein, FKBPL, and AD-01, offer a promising and alternative approach for targeting both CD44 positive tumours and vasculature networks." (PMID 23457460, 2013). "The lack of correlation of FKBPL with tumor grade, clinical stage, DMI, and LVI, might be due to limiting factors of the study, including that most of the EECs were of low grade (grade 1 and 2) and stage I, producing a group of biologically similar tumors." (PMID 36295491, 2022). "FKBPL overexpressing xenografts had increased vessel diameter and segment length whilst the number of branch points was significantly reduced, indicative of reduced vessel density which correlated with reduced tumour growth (data not shown) in comparison to parental xenografts." (PMID 23457460, 2013). "We have previously shown that FKBPL is secreted from HMEC-1 and lung epithelial cells, L132, but not from the tumour cell line, MDA-MB-231." (PMID 23457460, 2013). "FKBPL is clearly divergent, with no PPIase activity, whilst retaining its tetratricopeptide repeat (TPR) domain, important for the interaction with the molecular chaperone Hsp90, and is emerging as a key negative regulator of tumor growth, angiogenesis and metastasis." (PMID 25906750, 2015).
hematological tumors (1 paper, 2025). "Our findings indicate that certain plasma proteins exhibit causative roles in various hematological tumors, specifically ISOC1 in 14 tumors, ADK in 11 tumors, FKBPL in 10 tumors, and BCL2 in 9 tumors." (PMID 41048997, 2025).
lung (1 paper, 2024). "We first performed western blot to examine the expression of FKBPL in two lung ADC cell lines, A549 and H1975." (PMID 38164287, 2024).